HNF1B (HNF1 homeobox B)
Description:
Transcription factor that binds to the inverted palindrome 5'-GTTAATNATTAAC-3'. Binds to the FPC element in the cAMP regulatory unit of the PLAU gene (By similarity). Transcriptional activity is increased by coactivator PCBD1.
Synonyms: HNF-1-beta; HNF-1B; TCF-2; vHNF1; TCF2; LFB3; HNF1beta; MODY5; HNF1β; ADTKD3; FJHN; HNF2; HPC11; LF-B3; RCAD; T2D
Tractability: No criterion of Open Targets' tractability assessment is met for any kind of drug.
Gene: Protein-coding gene on chromosome 17 (37,686,431 to 37,745,091, reverse strand). Ensembl gene ENSG00000275410.
Subcellular location: Nucleus
Subcellular location (Human Protein Atlas): Nucleoplasm; Vesicles
Pathways (Reactome):
Developmental Biology: Developmental Lineage of Multipotent Pancreatic Progenitor Cells; Developmental Lineage of Pancreatic Acinar Cells; Developmental Lineage of Pancreatic Ductal Cells; Nephron development; Regulation of gene expression in early pancreatic precursor cells; Regulation of gene expression in late stage (branching morphogenesis) pancreatic bud precursor cells
Gene Ontology:
Molecular function: DNA-binding transcription factor activity; protein binding; DNA-binding transcription factor activity, RNA polymerase II-specific; RNA polymerase II cis-regulatory region sequence-specific DNA binding; cis-regulatory region sequence-specific DNA binding; DNA binding; identical protein binding; promoter-specific chromatin binding; transcription cis-regulatory region binding
Biological process: kidney development; positive regulation of DNA-templated transcription; positive regulation of transcription initiation by RNA polymerase II; pronephric nephron tubule development; pronephros development; regulation of pronephros size; regulation of transcription by RNA polymerase II; animal organ development; insulin secretion; liver development; pancreas development; system development
Cellular component: nucleoplasm; nucleus; chromatin; transcription regulator complex
Genetic constraint (gnomAD): Loss-of-function variants: 8 observed, 60.33 expected, observed/expected ratio (o/e) 0.13, 90% interval 0.077 to 0.24. The upper end of that interval is the gene's LOEUF score, 0.24, which puts it in group 1 of 6, group 1 being the genes least tolerant of losing a copy. Missense variants: 562 observed, 714.14 expected, observed/expected ratio (o/e) 0.79, 90% interval 0.73 to 0.84. Synonymous variants: 314 observed, 291.98 expected, observed/expected ratio (o/e) 1.08, 90% interval 0.98 to 1.18.
Gene-disease validity (ClinGen):
ClinGen rates the evidence that HNF1B causes each of these diseases.
renal cysts and diabetes syndrome (autosomal dominant): Definitive. Renal cysts and diabetes syndrome (RCAD) is a rare form of maturity-onset diabetes of the young (MODY) characterized clinically by heterogeneous cystic renal disease and early-onset familial non-autoimmune diabetes.
Homologues: Orthologues: chimpanzee HNF1B (99% identical), macaque HNF1B (99% identical), guinea pig HNF1B (98% identical), dog HNF1B (98% identical), rat Hnf1b (97% identical), pig HNF1B (96% identical), mouse Hnf1b (92% identical), rabbit HNF1B (91% identical), tropical clawed frog hnf1b (88% identical), zebrafish hnf1ba (81% identical), zebrafish hnf1bb (68% identical). Paralogues in human: HNF1A (56% identical).
Diseases named in the same sentence as HNF1B in open-access papers:
HNF1B is named in the same sentence as 345 diseases in open-access papers, as found by Europe PMC text mining. Sharing a sentence is not in itself a finding about the gene and the disease. The quoted sentences say what the papers report.
diabetes (168 papers, 2007 to 2026). "Overall, 36/486 probands (7.4%) with genetically confirmed monogenic diabetes in the NMR carried a P/LP HNF1B sequence variant or 17q12del." (PMID 42278591, 2026). "Overall, this case contributes to the growing understanding of the clinical and genetic spectrum of HNF1B-associated conditions and underscores the value of genetic testing in atypical diabetes cases." (PMID 39976628, 2025). "Variants in syndromic diabetes genes accounted for 19 % of all monogenic diabetes cases, with the mitochondrial m.3243 A > G variant and HNF1B variants being the most common." (PMID 39835172, 2025). "Thirdly, we only incorporated 20 patients with monogenic diabetes, which is difficult to highlight the effect of mutations in HNF1β, HNF4A, and HNF1A genes associated with Lp(a) expression on Lp(a) concentration in patients with early-onset T2DM." (PMID 40370778, 2025). "In patients with HNF1B variants, diabetes is the first feature occurring in 50% of the patients, while kidney disease occurs first in the other half of the cases." (PMID 41009948, 2025). "Pediatricians should consider genetic testing for HNF1B mutations when children are diagnosed with diabetes and have renal abnormalities, hyperlipidemia, and hyperparathyroidism." (PMID 41809577, 2025). "Variants in the hepatocyte nuclear factor 1 beta (HNF1B) gene represent approximately 1–6% of monogenic diabetes causes." (PMID 39976628, 2025). "The HNF1B gene (MIM: 189907) on chromosome band 17q12 is associated with diabetes and prostate cancer." (PMID 39975073, 2025). "Of the four children with HNF1B mutations identified by familial mutation analysis or based on renal disease, two developed diabetes during the course of the study." (PMID 41809577, 2025). "Context: Mutations in hepatocyte nuclear factor 1B (HNF1B) are rare but they are known to cause structural renal disease and diabetes mellitus." (PMID 41809577, 2025). "Maturity-onset diabetes of the young type 5 (MODY5) is one of the monogenic forms of diabetes and is caused by haploinsufficiency of the HNF1B gene." (PMID 40166445, 2025). "HNF1B mutations can mimic Gitelman syndrome, but features such as early kidney issues and a family history of diabetes or cysts help differentiate them." (PMID 40777730, 2025). "HNF1B-associated renal disease presents with a diverse array of renal and extrarenal manifestations, prominently featuring cystic kidney disease and diabetes mellitus." (PMID 38674137, 2024). "The degree of insulin deficiency among individuals with HNF1B-diabetes and MD can range from mild hyperglycemia to absolute insulin deficiency." (PMID 39025920, 2024). "In contemporary practice, all patients with renal cysts, genital tract malformations, hypomagnesemia, liver test abnormalities and diabetes should undergo screening for HNF1B-associated disease." (PMID 38674137, 2024). "Based on the patient history of diabetes and hyperlipidemia and positive family history of diabetes and kidney disease, it appears that this mutation in the HNF1B gene is a pathogenic one associated with HNF1B-related MODY." (PMID 37511676, 2023). "Diabetes runs in many family members, i.e., the patient’s father was diagnosed with an HNF1B-related MODY mutation during the family screening." (PMID 37511676, 2023). "In previous observations, the most common health condition associated with HNF1B mutation were renal cysts and diabetes syndrome (development of cysts in the kidneys together with the development of diabetes)." (PMID 37511676, 2023). "The identification of two distinct genetic mutations linked to HNF1B-related MODY is an important finding because it sheds light on the underlying genetic mechanisms that contribute to this form of diabetes." (PMID 37511676, 2023). "The association of the 17q12 deletion with diabetes and decreased kidney function is known to be caused by haploinsufficiency of HNF1B." (PMID 36109160, 2023).
diabetes (continued). "HNF1B is important during pancreas development where its mutation causes monogenic diabetes in humans, and functions upstream of SOX9 and NEUROG3 reflecting its late regulatory role during PP development." (PMID 36749553, 2023). "SNP association analysis in the 17q12 region implicated changes to HNF1B as causing decreased eGFR (NC_000017.11:g.37741642T>G, rs12601991, p=4×10−21) and diabetes (NC_000017.11:g.37741165C>T, rs7501939, p=6×10−17)." (PMID 36109160, 2023). "Case 38 bears a 17q12 deletion that includes HNF1B; this abnormality arises spontaneously in 70% of cases and has been associated with high frequency of diabetes (63%) with onset in adulthood." (PMID 36178555, 2023). "Of note, patients with HNF1B nephropathy who undergo renal transplant are at increased risk of developing post-transplant diabetes mellitus (PTDM)." (PMID 36672242, 2023). "We identified seven adults with monogenic diabetes (3% [95% CI 1%, 7%]; two with HNF1B-related diabetes and five with the mitochondrial DNA mutation m.3243A>G)." (PMID 36355183, 2023). "Within the broad clinical spectrum described by patients with HNF1B mutations, age at diabetes diagnosis was found to be greater compared to patients with T1DM (median 13.5 versus 8.8 years; P = 0.00001; n.s versus T2DM)." (PMID 37016461, 2023). "Three studies tested for variations in HNF1B in larger samples of patients with pathogenic kidney phenotypes and diabetes." (PMID 36969268, 2023). "Among 201 patients with an HNF1B mutation, one study showed that while 82% presented with diabetes, 44% also had stage 3–4 renal impairment and 21% end-stage renal disease at diagnosis." (PMID 35618782, 2022). "Five participants presented other monogenic diabetes mutations (HNF1B: n = 2; PDX1: n = 2; APPL1: n = 1) but were excluded from the analysis." (PMID 35822264, 2022). "Hydroxyeicosatetraenoic acid—found to be elevated among HNF1B-MODY patients was previously linked with diabetes-induced endothelial dysfunction." (PMID 35179657, 2022). "The mitochondrial m.3243A>G and mutations in HNF1B were responsible for the majority of mutations in syndromic diabetes genes." (PMID 34789499, 2022). "For example, a patient with an HNF1B mutation will commonly have diabetes and renal structural features such as renal cysts, hypoplasia and aplasia." (PMID 34789499, 2022). "We also identified 14 cases with mutations in syndromic monogenic diabetes genes other than m.3243A>G and HNF1B." (PMID 34789499, 2022). "The research described HNF1β-related diabetes and associated phenotypes and assessed genotype/phenotype correlations at diagnosis and in the long term." (PMID 35480487, 2022). "The combination of diabetes with congenital anomalies in the kidney (cysts) and urinary tract is the most consistent clinical presentation in individuals with HNF1B mutations." (PMID 35052457, 2022). "Some researchers have reported variants of the HNF1B gene in familial cases of CUAs, often associated with kidney malformations and Maturity Onset Diabetes of the Young (MODY)." (PMID 35883945, 2022). "All probands with UMOD/REN/HNF1B variants had a clinical history of hyperuricemia and increased plasma creatinine, and the proband with HNF1B variation also presented with diabetes mellitus, hypokalemia and an abnormal liver test." (PMID 33574344, 2021). "Diabetes complications and cardiovascular risk factors are highly prevalent in individuals with HNF1B-MODY." (PMID 34299172, 2021). "When a pathogenic variant is found in certain genes, screening for ocular coloboma or diabetes caused by PAX2 or HNF1B respectively, should be recommended." (PMID 36939782, 2021). "Though diabetes secondary to HNF1β variant develops typically during adolescence or early adulthood; two of the MODY5 patients in our study developed diabetes at the age of 4 and 9 years, respectively." (PMID 34373539, 2021).
diabetes (continued). "Heterozygous mutations in HNF1B in humans result in a multisystem disorder, including pancreatic hypoplasia and diabetes mellitus." (PMID 34450036, 2021). "The pathophysiology of diabetes mellitus in patients with HNF1B mutations is mainly attributed to β cell dysfunction and reduced insulin secretion, which is likely to be a consequence of pancreatic hypoplasia." (PMID 34450036, 2021). "These patients with variants can be associated with diabetes phenotypes or clinical features involving the GCK or HNF1β gene, such as age of onset of diagnosis, level of secretion of insulin during an OGTT, or renal dysplasia or abnormality." (PMID 34746319, 2021). "The severity and the age of the onset of diabetes can vary greatly depending on the types of mutations involved in the HNF1b gene; further, the extent of kidney damage can also be equally heterogeneous." (PMID 33259036, 2021). "We describe here the use of a well-controlled hiPSC pancreatic differentiation model to elucidate the molecular mechanisms underlying HNF1B-associated diabetes and pancreatic hypoplasia." (PMID 34450036, 2021). "In this article, Rodríguez-Seguí and colleagues use an hiPSC pancreatic differentiation model to study the mechanisms underlying HNF1B-associated diabetes." (PMID 34450036, 2021). "A more detailed study of the interplay between HNF1A-AS1 and HNF1A expression in this model of HNF1B-associated diabetes is an exciting area for future research." (PMID 34450036, 2021). "This case underlines that newborns carrying HNF1b mutations must be constantly and carefully monitored over time even if born to normo-glycemic mothers to possibly detect the early signs of diabetes." (PMID 33259036, 2021). "Analogously, the rs4430796 risk allele decreases PAX6 binding and downregulates the expression of HNF1B, leading to an elevated risk of diabetes." (PMID 33919522, 2021). "The main difference among the studies resides in the strategy used to model HNF1B-associated diabetes." (PMID 34450036, 2021). "In this study, we established a well-controlled human induced pluripotent stem cell (hiPSC) pancreatic differentiation model to elucidate the molecular mechanisms underlying HNF1B-associated diabetes and pancreatic hypoplasia." (PMID 34450036, 2021). "Here we used a well-controlled human induced pluripotent stem cell pancreatic differentiation model to elucidate the molecular mechanisms underlying HNF1B-associated diabetes." (PMID 34450036, 2021). "Maturity-onset diabetes of the young type 5 (MODY5) is one of the well-known extrarenal manifestations of HNF1B mutations, and the combined phenotypes of renal cysts and diabetes are referred to as RCAD syndrome." (PMID 32708349, 2020). "HNF1b is crucial in modulating pancreatic multipotent progenitor cells and generation of endocrine precursors and is associated with maturity-onset of Diabetes of the Young-5 (MODY5)." (PMID 32527043, 2020). "For example, in the TF–miRNA regulatory network of diabetes mellitus, we found all of the TFs (FOS, PPARG, HNF1B) with high degree centralities were validated to be associated with diabetes mellitus in related publications." (PMID 30371815, 2019). "Patients with pathogenic mutation in HNF1-B also had concomitant conditions including diabetes (n = 2) and abnormal LFTs (n = 2)." (PMID 31509055, 2019). "Of note, among the 15 HNF1B cases we identified, 10 had an HNF1B whole gene deletion, known to be associated with a normal renal function at diabetes diagnosis in 75% of cases, but a severe diabetes phenotype." (PMID 31291970, 2019). "Mutations in the HNF1B gene usually cause diabetes maturity‐onset diabetes of the young type 5 (MODY5)." (PMID 31056860, 2019). "Despite the presence of diabetes, the renal dysfunction found in carriers of HNF1β mutations is thought to be caused by renal development abnormalities rather than diabetic renal disease." (PMID 29764441, 2018).
diabetes (continued). "The diabetic phenotype associated with HNF1β mutations is also equally heterogenous, with severity of glycaemia ranging from impaired glucose tolerance to diabetes requiring insulin therapy." (PMID 29764441, 2018). "The most common pathological expressions of HNF1B mutations are renal cysts associated with early onset diabetes." (PMID 28647851, 2018). "This has mainly been studied in small series of patients with HNF1B mutations and diabetes using indirect tests of pancreatic function, usually faecal elastase-1 measurement in stool." (PMID 30094008, 2018). "Faecal elastase-1 measurements were compared in individuals with HNF1B-associated disease according to diabetes status." (PMID 30094008, 2018). "Of note, the same missense mutation in HNF1β has also been detected in an unrelated Maltese female referred for monogenic diabetes screening." (PMID 29764441, 2018). "In humans, mutations in the HNF1B gene were described in a monogenic form of diabetes, namely maturity-onset diabetes of the young type 5 (MODY5)." (PMID 26329304, 2015). "An atypical variant of FJHN, associated with diabetes and renal cysts, has been linked to mutations in HNF-1β on chromosome 17q12 (MIM 189907)." (PMID 24886545, 2014). "At this time, the relationship between obesity, diabetes, and PCa is poorly understood, and so is the contribution of the HNF1B variants to the risk." (PMID 24386569, 2013). "In contrast, mutations in HNF1B, which account for approximately 5% of cases of monogenic diabetes, lead to clinical syndromes more reflective of the widespread expression of this transcription factor." (PMID 23766565, 2013). "Hnf-1b results in a distinct form of diabetes that is associated with a spectrum of related defects including renal cysts and internal defects in uterus and genitalia." (PMID 20587063, 2010). "Consequently, the hallmark of HNF1B-related disease is the presence of renal cysts, often detectable prenatally, alongside diabetes, which involves both insulin deficiency and pancreatic atrophy." (PMID 41614934, 2026). "Similarly, GATA6 and HNF1B mutations present with diabetes associated with structural defects in the heart and kidneys, respectively." (PMID 41614934, 2026). "Mutations in HNF1A, HNF4A, and HNF1β genes involved in Lp(a) expression account for more than 50% of monogenic diabetes with a known genetic cause, which may lead to the complexity of concentrations of Lp(a) in patients with T2DM." (PMID 40370778, 2025). "The early-onset T2DM cohort included patients with monogenic diabetes resulting from mutations in the HNF1β, HNF4A, and HNF1A genes associated with Lp(a) expression, which may help explain the lower levels of Lp(a)." (PMID 40370778, 2025). "Two of them occurred in GCK-MODY and one in HNF1B-MODY variants of monogenic diabetes." (PMID 40649834, 2025). "Patients with HNF1B sequence variants are usually distinguishable because they present with extra-renal manifestations such as diabetes, gout and hyperparathyroidism, hypomagnesemia, elevated liver enzymes, and congenital anomalies of the kidney and urogenital tract." (PMID 38707821, 2024). "An HNF1B mutation could also be one of the potential factors that caused the TNDM in our patient because the pancreatic hypoplasia was coexistent with diabetes, but it was excluded by the NGS test that was performed." (PMID 38998792, 2024). "Likewise, heterozygous mutations in other transcription factors (e.g., GATA6, HNF1B) have been reported to cause diabetes as a consequence of their effects on early pancreatic development." (PMID 38509065, 2024). "Likewise, Hnf1b, Gata4/Gata6, Pdx1 or Mnx1-deficient mice fail to develop pancreas of normal size and rather develop diabetes." (PMID 39322760, 2024).